RAB41 (RAB41, member RAS oncogene family)
Description:
The small GTPases Rab are key regulators of intracellular membrane trafficking, from the formation of transport vesicles to their fusion with membranes. Rabs cycle between an inactive GDP-bound form and an active GTP-bound form that is able to recruit to membranes different sets of downstream effectors directly responsible for vesicle formation, movement, tethering and fusion. RAB41 is required for normal Golgi ribbon organization and ER-to-Golgi trafficking.
Tractability: Antibody: its Gene Ontology location is reachable by antibodies, with high confidence.
Gene: Protein-coding gene on chromosome X (70,282,093 to 70,285,002, forward strand). Ensembl gene ENSG00000147127.
Subcellular location: Cytoplasm
Subcellular location (Human Protein Atlas): Cytosol; Plasma membrane; Vesicles
Pathways (Reactome):
Metabolism of proteins: RAB geranylgeranylation
Vesicle-mediated transport: Intra-Golgi traffic
Gene Ontology:
Molecular function: G protein activity; protein binding; GTPase activity; GTP binding
Biological process: intra-Golgi vesicle-mediated transport; protein localization to Golgi membrane; retrograde transport, endosome to Golgi; retrograde vesicle-mediated transport, Golgi to endoplasmic reticulum
Cellular component: cytoplasm; cytosol; Golgi membrane; Golgi apparatus
Homologues: Orthologues: chimpanzee RAB41 (99% identical), macaque RAB41 (96% identical), tropical clawed frog rab41 (60% identical). Paralogues in human: RAB6B (61% identical), RAB6A (60% identical), RAB6C (55% identical), RAB6D (55% identical), RAB37 (36% identical), RAB10 (35% identical), RAB26 (34% identical), RAB5A (34% identical), RAB8B (33% identical), RAB5B (33% identical), RAB5C (32% identical), RAB8A (32% identical), and 56 more.
Diseases named in the same sentence as RAB41 in open-access papers:
RAB41 is named in the same sentence as 7 diseases in open-access papers, as found by Europe PMC text mining. Sharing a sentence is not in itself a finding about the gene and the disease. The quoted sentences say what the papers report.
lung adenocarcinoma (1 paper, 2022). A carcinoma that arises from the lung and is characterized by the presence of malignant glandular epithelial cells. "RAB41 plays an essential role in membrane trafficking, high expression of which is associated with poor clinical results of lung adenocarcinoma." (PMID 35237504, 2022).
cancer (3 papers, 2022 to 2023). A tumor composed of atypical neoplastic, often pleomorphic cells that invade other tissues. "RAB41 is a member of RAB family, which frequently acts as oncogenes in various cancer." (PMID 35237504, 2022).
bacterial infection (1 paper, 2023). "Rab41 is a Rab6-like protein reported to be localized to the cytosol and Golgi apparatus, where it is thought to regulate Golgi organization and endoplasmic reticulum (ER)–Golgi trafficking; however, its localization and function during bacterial infection remains undefined." (PMID 37802980, 2023).
RAB41 also shares sentences with these, for which no sentence is quoted: infection (1 paper); oral cancer (1); Oral Squamous Cell Carcinoma (1); periodontitis (1).